PLPP7 (phospholipid phosphatase 7 (inactive))
Description:
Plays a role as negative regulator of myoblast differentiation, in part through effects on MTOR signaling. Has no detectable enzymatic activity (By similarity).
Synonyms: C9orf67; PPAPDC3; MGC12921; FLJ14662; NET39
Tractability: Antibody: UniProt predicts a signal peptide or a membrane-spanning region.
Gene: Protein-coding gene on chromosome 9 (131,289,459 to 131,359,022, forward strand). Ensembl gene ENSG00000160539.
Subcellular location: Nucleus envelope; Endoplasmic reticulum membrane; Membrane
Subcellular location (Human Protein Atlas): Nucleoplasm; Vesicles
Gene Ontology:
Molecular function: sphingosine-1-phosphate phosphatase activity
Cellular component: membrane; nuclear envelope; endoplasmic reticulum membrane
Genetic constraint (gnomAD): Loss-of-function variants: 12 observed, 14.84 expected, observed/expected ratio (o/e) 0.81, 90% interval 0.52 to 1.31. The upper end of that interval is the gene's LOEUF score, 1.31, which puts it in group 5 of 6, group 1 being the genes least tolerant of losing a copy. Missense variants: 358 observed, 354.8 expected, observed/expected ratio (o/e) 1.01, 90% interval 0.93 to 1.1. Synonymous variants: 174 observed, 149.07 expected, observed/expected ratio (o/e) 1.17, 90% interval 1.03 to 1.32.
Homologues: Orthologues: chimpanzee PLPP7 (100% identical), macaque PLPP7 (99% identical), pig PLPP7 (95% identical), mouse Plpp7 (95% identical), dog PLPP7 (94% identical), rat Plpp7 (94% identical), rabbit PLPP7 (93% identical), guinea pig PLPP7 (93% identical), tropical clawed frog plpp7 (73% identical), zebrafish plpp7a (66% identical), zebrafish PLPP7 (60% identical), Caenorhabditis elegans T13C5.6 (25% identical), and 1 more. Paralogues in human: PLPP6 (51% identical), SGPP2 (17% identical), SGPP1 (17% identical).
Diseases named in the same sentence as PLPP7 in open-access papers:
PLPP7 is named in the same sentence as 12 diseases in open-access papers, as found by Europe PMC text mining. Sharing a sentence is not in itself a finding about the gene and the disease. The quoted sentences say what the papers report.
muscular dystrophy (3 papers, 2021 to 2023). Muscular dystrophy (MD) refers to a group of more than 30 genetic diseases characterized by progressive weakness and degeneration of the skeletal muscles that control movement. "Intriguingly, mutations in PLPP7, TMEM38A, and TMEM201 have been identified in muscular dystrophy patients with an EDMD-like phenotype, which highlights the importance of these proteins in muscle disease." (PMID 36699009, 2022).
lung carcinoma (1 paper, 2017). "Conversely, the expression levels of PLPP1, PLPP3 and PLPP7 were decreased to varying degrees compared with those in the ANT, indicating that different members of the PLPP family have oncogenic or tumor-suppressive roles in the development of lung carcinoma." (PMID 28851360, 2017).
PLPP7 also shares sentences with these, for which no sentence is quoted: cancer (2 papers); Emery-Dreifuss muscular dystrophy (2); tumor (2); cardiomyopathy (1); congenital muscular dystrophy (1); congenital myopathy (1); Duchenne muscular dystrophy (1); laminopathy (1); myopathy (1); Obesity (1).